ENSG00000228933 (novel transcript)
Gene: Long non-coding RNA gene on chromosome X (27,016,335 to 27,399,033, reverse strand). Ensembl gene ENSG00000228933.
Gene Ontology:
Biological process: SRP-dependent cotranslational protein targeting to membrane, signal sequence recognition
Cellular component: signal recognition particle, endoplasmic reticulum targeting